TET2 (tet methylcytosine dioxygenase 2)
Diseases named in the same sentence as TET2 in open-access papers (continued):
Sharing a sentence is not in itself a finding about the gene and the disease.
lymphoma (continued). "TET2 has been known to orchestrate the regulation of promoter methylation status by converting 5mc to 5hmc, and function as a tumor suppressor in myeloma and lymphoma." (PMID 28915632, 2017). "Together these findings suggest that TET2 mutations might be a lymphoma clone‐specific event, not at the haematopoietic stem/progenitor cell level." (PMID 39722652, 2025). "Similarly, the mutational profile of FTCL seems to be similar to other nodal TFH lymphomas with mutations in TET2, DNMT3A, and RHOAG17V, but not in IDH2 which are usually restricted to AITL." (PMID 36793612, 2023). "Multiple mutated TET2 alleles (median = 2; range 1–15 unique variants) were detected in the same patients, with variant allele frequencies (VAF) spread between an approximation of putative truncal lymphoma lesions (e.g., RHOAG17V) and the limit of detection of the assay (~0.2%)." (PMID 35459873, 2022). "Therefore, we attempted to elucidate the impact of TET2-CH on AIC in patients with lymphoma." (PMID 35492814, 2022). "Consistent with the observation that patients with TET2 mutated lymphomas harbor the same mutation in their HSC, the contribution of these alterations to lymphomagenesis was studied in vivo by engineering the conditional loss of Tet2 in HSCs or at later stages of B-cell development." (PMID 34456919, 2021). "Interestingly, reduced accumulation of the C to T mutations by inactivation of AID blocked development of B-cell malignancies in aging TET2-deficient mice, implying that AID might be a therapeutic targeting candidate for lymphoma, including AITL." (PMID 34581268, 2021). "Tet2 knockout mice partially phenocopied DLBCL patients, characterized by downregulation of antigen presentation genes/interferon pathway, lymphoma-like transcriptional profiles similar to CREBBP-mutant patients, and a failure at the germinal center exit." (PMID 35159097, 2022). "Mutations related to the RAS family (RHOA) and those related to epigenetic regulators (IDH2, DNMT3A, and TET2) were shown mainly in AITL and other TFH lymphomas." (PMID 33990228, 2021). "Consistent with this notion, in AITL animal models, TET2 disruption or RHOAG17V expression alone failed to induce AITL development; however, AITL-like lymphoma developed once TET2 disruption and RHOAG17V expression were combined." (PMID 34581268, 2021). "Notably, mutations related to the RAS family (RHOA) and those related to epigenetic regulators (IDH2, DNMT3A, and TET2) were found mainly in AITL and other TFH lymphomas." (PMID 33990228, 2021). "In the first model, AITL-like lymphoma did not naturally develop: bone marrow transplantation from Tet2-Rhoa-CD4 mice to syngenic mice followed by immunization with sheep red blood cells (SRBCs) was required for development of AITL-like lymphoma in recipients." (PMID 32704161, 2020). "Although T-cell lymphoma with Tfh phenotypes is seen following Tet2 downregulation in mice, histology of lymphoma tissues does not resemble AITL." (PMID 32704161, 2020). "Work with human samples and murine models has shown that TET2 deficiency does not trigger full-blown malignancies but predisposes to the development of tumors such as MPN, MDS and lymphoma." (PMID 25632305, 2015). "Perhaps not surprisingly, TET2 and CREBBP mutations are mutually exclusive in human lymphomas." (PMID 38124747, 2023). "Adoptive transfer of wild-type or TET2-deficient T cells retrovirally transduced to overexpress RhoA-G17V into T-cell deficient murine hosts resulted in CD4+ T cell expansion, disruption of peripheral T cell homeostasis and eventually lethal inflammation but no lymphoma was noted." (PMID 37841428, 2023). "Importantly, among Tfh lymphomas, IDH2R172 mutations are mostly confined to AITL and are rare in FTCL and PTCL-NOS with Tfh phenotype or GEP, unlike recurrent mutations in TET2, DNMT3A, and RHOA, which are common to all types of Tfh lymphomas." (PMID 32704161, 2020).
breast carcinoma (69 papers, 2014 to 2026). "Low TET2 expression was also associated with poor OS in early‐stage breast cancer (HR [95% CI] = 2.59 [0.352–19.172], p = 0.067)." (PMID 40116537, 2025). "As E2-treatment resulted in the rapid loss of global DNA methylation through the upregulation of TET2 in breast cancer cell." (PMID 38374066, 2024). "Numerous studies have shown that E2 induces a rapid loss of global DNA methylation by upregulating TET2 in breast cancer cells." (PMID 38374066, 2024). "Using these models, we identified one APA event in gene TET2 that showed an association with overall breast cancer risk at the Bonferroni-corrected significance of P < 1.5 × 10−5 (0.05/3309)." (PMID 38697998, 2024). "E2-treatment has resulted in the rapid loss of global DNA methylation through the upregulation of TET2 in breast cancer cells." (PMID 38374066, 2024). "In breast cancer cells, miR-660-5p targets TET2 and is associated with a higher stage and an increased vascular invasion in breast cancer patients." (PMID 33805247, 2021). "CCLE data analysis showed that TET2 mRNA expression levels are negatively associated with PD-L1 mRNA expression levels in 57 breast cancer cell lines (p = 0.0031)." (PMID 34064441, 2021). "A recent GWAS analysis revealed a risk SNP associated with breast cancer is located within the TET2 gene." (PMID 34885145, 2021). "Given that luminal breast cancer mainly occurs in old population, it is of great interest to investigate the relationship between the hematopoietic TET2 mutations and the initiation and progression of breast cancer." (PMID 34885145, 2021). "Here, the authors show that TET2–FOXP1 complex mediates demethylation of genes involved in luminal lineage commitment and endocrine response, underlying a role of TET2 loss in endocrine resistant breast cancer." (PMID 32934200, 2020). "Breast cancer samples with TET2 mutations showed lower 5hmC levels than those of samples without TET2 mutations." (PMID 32774324, 2020). "Together these data suggest that loss of TET2 contributes to loss of ERα expression and defective ER signaling that confers endocrine resistance in mammary epithelial cells and breast cancer cells." (PMID 32934200, 2020). "The four TSGs: CBLC, CDH11, LZTR1, and TET2 previously shown to be most frequently mutated in 1KGP were also observed to display changes in ASE in breast cancer." (PMID 32064050, 2020). "As a result, this study elucidates a role for TET2 in governing luminal cell differentiation and endocrine response that underlies breast cancer resistance to anti-estrogen treatments." (PMID 32934200, 2020). "Retinoic acid treatment of the nontumorigenic, immortalized mammary epithelial cell line, MCF12A and the non-invasive breast cancer cell line T47D induces the association of the RA nuclear receptor RARβ with a methylcytosine dioxygenase (TET2)." (PMID 31590252, 2019). "Attenuation of TET2 is also linked to malignant breast tumor development." (PMID 40116537, 2025). "Analyses by subtypes of breast cancer identified TET2 from APA-WAS in association with ER-negative breast cancer risk at the Bonferroni-corrected significant level and BRD9 from spTWAS in association with ER-negative and TNBC subtypes at the Bonferroni-corrected significant level." (PMID 38697998, 2024). "Therefore, our work expands our current understanding of the pleiotropic role of TET2 loss in breast cancer pathogenesis, especially as it relates to immune evasion." (PMID 34064441, 2021). "Deficiency in TET2 expression/activity may be used as a potential biomarker to predict tamoxifen resistance in human breast cancer." (PMID 32934200, 2020). "As a result, this study provides a role for TET2 that underlies breast cancer resistance to anti-estrogen treatments, and our in vivo Tet2 deletion breast cancer mouse model will be a valuable tool for studying the associated mechanism(s) for development of anti-cancer therapies." (PMID 32934200, 2020).
breast carcinoma (continued). "We have also shown that loss of TET2 contributes to impaired luminal lineage commitment, promoted mammary tumor development with deficient ERα expression, and confers tamoxifen resistance in a Tet2 deletion-PyMT breast cancer mouse model." (PMID 32934200, 2020). "The expression of 5hmC in breast cancer of mutated TET2 was decreased." (PMID 32375881, 2020). "TET2 loss promotes tumorigenesis of breast cancer cells by regulating caspase-4." (PMID 32774157, 2020). "Such evidence suggested that it is plausible that rare coding variants in TET2 could lead to compromised TET2 function and involvement in breast cancer susceptibility." (PMID 29316957, 2018). "TET2 mutations, such as gene deletion, occur in chronic myelomonocytic leukemia, acute myeloid leukemia, and myelodysplastic syndromes as well as in solid tumors, including clear-cell renal cell carcinoma, prostate cancer, and breast cancer." (PMID 26207381, 2015). "Since deletion of TET2 leads to impaired ERα expression, we next asked whether loss of TET2 expression conferred endocrine resistance in mammary epithelial cells and breast cancer cells." (PMID 32934200, 2020). "In breast cancer, TET2 recruits HDAC1/2 to remove H3K27ac at the CD274 promoter, thereby repressing its transcription." (PMID 41409271, 2025). "Loss of TET2 caused an impressive decrease in the 5hmC levels, especially at ER cis-regulatory elements, which emphasized again the essential role of TET2 in mediating the transcription of ER target genes particularly in breast cancer cells." (PMID 40014756, 2025). "Both TET2 and BRD9 are located at previously GWAS-identified breast cancer risk loci (lead variants rs62331150 and rs2853669)." (PMID 38697998, 2024). "Another study, which concerns peripheral blood samples of breast cancer patients has revealed the increase in only TET2 and TET3 expression." (PMID 38499584, 2024). "While TET2 and TET3 have the potential to influence estrogen receptors and luminal-like transformation in breast cancer, TET1 appears to be more associated with hormone-independent breast cancer." (PMID 39201247, 2024). "The TET2-interacting proteins IDAX/CXXC4 and RINF/CXXC5 are overexpressed in a number of solid tumours, including breast cancer and colorectal cancer, and have been reported to negatively affect TET2 stability and function." (PMID 37667220, 2023). "TET2 expression is decreased in liver cancer, breast cancer, lung cancer, prostate cancer and other solid tumors, leading to a decrease in the content of its catalytic product 5hmC, which is closely related to tumor development." (PMID 35480097, 2022). "As expected, lysosomal gene mRNA levels were positively correlated with TFEB and TFE3 levels and negatively correlated with MYC and TET2 levels in breast cancer patients (normal-like tumors, n = 639)." (PMID 35351824, 2022). "Similar to DNMT3A/B, TET2 is a potential biomarker for ER+ breast cancer progression and metastasis." (PMID 35453496, 2022). "Collectively, these data indicate that enforced TET2 activity in MCF-7 breast cancer cells triggers a pre-activated antiviral state that predisposes cells to death induced by ABCE1 inactivation." (PMID 35351824, 2022). "In vitro studies on breast cancer have reported that TET2 knockout upregulates the expression of programmed death-ligand 1 (PD-L1) in MCF7 cells." (PMID 35223782, 2022). "Cancer cells have their own transcriptional programs, and we sought to alter such a cancer-specific program by enforcing expression of the catalytic domain (CD) of the methylcytosine dioxygenase TET2 in breast cancer cells." (PMID 35351824, 2022). "Survival analysis between TET2 high expression and low expression groups in patients with breast cancer (Kaplan-Meier Plotter)." (PMID 35223782, 2022). "Enforcing TET2 activity reduced the tumorigenic potential of MCF-7 breast cancer cells and triggered an antiviral state and a lysosomal storage disease–like phenotype that predisposed cells to death." (PMID 35351824, 2022).
breast carcinoma (continued). "TET2 has been reported to serve as a co-activator of ERα by de-methylating and maintaining low CpG methylation levels in breast cancer cell lines." (PMID 35372016, 2022). "Collectively, these data indicated a prominent role of a TET2/MYC cross-talk in controlling lysosomal activity in breast cancer cells and impeding survival upon autophagy induction." (PMID 35351824, 2022). "Expression of NSUN1, NSUN2, NSUN5, DNMT1, DNMT3A, DNMT3B, and ALYREF was significantly increased, but DNMT2 and TET2 expression was markedly decreased in breast cancer tissues when compared with normal breast tissues." (PMID 35812757, 2022). "The coordinated down-regulation of lysosomal genes by TET2 CD, although of a low magnitude for each individual gene, is likely to trigger a lysosomal storage disease–like state in breast cancer cells." (PMID 35351824, 2022). "In a breast cancer cell line, TET2 was reported as a component of the estrogen receptor (ER)/GATA3 complex and was shown to be recruited in a GATA3-dependent manner." (PMID 34158086, 2021). "Surprisingly, we found that TET2 is a suppressor of PD-L1 gene transcription in breast cancer cells." (PMID 34064441, 2021). "This is correlated with reduced TET2 activity in lung, prostate, pancreatic, liver, and breast cancers when compared to the surrounding tissue." (PMID 33805247, 2021). "Although our work identifies that TET2 acts as a scaffold protein for the negative regulation of PD-L1 gene transcription in breast cancer cells, it is still unclear how TET2 itself is recruited to the PD-L1 promoter." (PMID 34064441, 2021). "Overall, our data demonstrate that TET2 functions as a negative regulator of PD-L1 gene transcription in breast cancer cells." (PMID 34064441, 2021). "To investigate the clinical significance of the TET2/PD-L1 axis, we analyzed the relationship between TET2 and PD-L1 expression levels in online breast cancer data." (PMID 34064441, 2021). "Taken together, our results identify a new epigenetic regulatory mechanism of PD-L1 gene transcription, linking the catalytic activity-independent role of TET2 to the anti-tumor immunity in breast cancer." (PMID 34064441, 2021). "Our data suggest that TET2 is able to modulate the H3K27ac level at the PD-L1 promoter in breast cancer cells." (PMID 34064441, 2021). "Next, we investigate the molecular mechanism through which TET2 inhibits PD-L1 gene transcription in breast cancer cells." (PMID 34064441, 2021). "Here, we identified TET2 as a negative regulator of PD-L1 gene transcription in breast cancer cells." (PMID 34064441, 2021). "Ali and colleagues found that loss of TET2 impairs E2/ERα-stimulated cell growth, indicating an oncogenic role of TET2 in ERα+ breast cancer." (PMID 34885145, 2021). "To further determine the role of TET2 in breast tumorigenesis, we generated a Tet2-deletion breast cancer mouse model by breeding our Tet2-deletion mouse model (MMTV-Cre;Tet2f/+) with an established breast cancer mouse model, MMTV-PyMT (PyMT)." (PMID 32934200, 2020). "Furthermore, Tet2 ablation-mediated accumulation MaSCs and bi-lineage progenitor cells are associated with poor differentiation tumor phenotype and endocrine resistance, which potentially underlies the development of intrinsic resistance to anti-estrogen treatments in aggressive breast cancer." (PMID 32934200, 2020). "Restoration of TET2 expression/activity is expected to provide therapeutic options for the cohort of breast cancer patients with intrinsic endocrine resistance." (PMID 32934200, 2020). "We collected the mammary glands from Tet2f/+;PyMT (WT-PyMT) and MMTV-Cre;Tet2f/+;PyMT (MUT-PyMT) at 5 weeks of age to verify the effects of Tet2 deletion on the early onset of mammary tumor development." (PMID 32934200, 2020).
breast carcinoma (continued). "Knockdown of TET2 in breast cancer cells decreases epithelial cell adhesion molecule and E-cadherin, increasing cell invasiveness." (PMID 30062102, 2018). "Here, we demonstrate that knockdown of KDM2A significantly increases the 5′-hydroxymethylcytosine (5′-hmc) level in genomic DNA and expression of tet-eleven translocation 2 (TET2) in various breast cancer cell lines." (PMID 28785073, 2017). "Moreover, in TET2-knockout breast cancer mice models, ER expression decreased considerably, which was in line with the endocrine resistance condition." (PMID 40014756, 2025). "One such study, using a full Tet2 KO mouse model, suggests a pro‐tumorigenic effect of Tet2 deletion via an IL‐6‐mediated immunosuppressive effect, which promotes tumor growth in models of hepatocellular carcinoma and breast cancer." (PMID 40517440, 2025). "In MCF7 cell lines, the activated ERα could firstly promote the expression of DNA methyltransferase (DNMT), which further mediated the promoter methylation of TET2, resulting in gene silencing as well as low levels of DNA hydroxymethylation in breast cancer." (PMID 40014756, 2025). "It has been demonstrated that TET2 is a direct target of E2 in breast cancer cells." (PMID 38374066, 2024). "It was demonstrated that TET2 is a direct target of ERα in breast cancer cells." (PMID 38374066, 2024). "We identified and validated TMEM41B as a target of miR-660-5p in breast cancer cells, which aligns with previous findings that miR-660-5p promotes breast cancer progression by targeting TET2 and activating the PI3K/AKT/mTOR pathway and the miR-660-5p/TFCP2/CDKN1A pathway." (PMID 39709500, 2024). "TET2 is a component of the estrogen receptor complex in multiple breast cancer models." (PMID 38374066, 2024). "Another study recently also found yhat TET2 could inhibit PD-L1 gene expression in breast cancer cells through histone deacetylation 34.However, the relationship between TET2 and PD-L1 in renal cancer is still unkown." (PMID 35173532, 2022). "However, when looking at the correlation between TET2 expression and antiviral response genes in breast cancer patients, a positive correlation was found only for EIF2AK2, MAVS, OTUD4, ABCE1, and RNase L expression levels." (PMID 35351824, 2022). "In contrast to TET1 and TET3, TET2 upregulation is frequently detected in ER+ breast cancer." (PMID 35453496, 2022). "Furthermore, KDM2A knockout significantly increases TET2 expression in various breast cancer cell lines." (PMID 35223782, 2022). "The expression level of TET2 is decreased in liver cancer, breast cancer, lung cancer, prostate cancer and other solid tumor tissues compared to normal tissues, and this downregulation decreases the content of its catalytic product 5-hmC, which is closely related to tumor development." (PMID 35480097, 2022). "Down-regulation of CLN3, CTSD, and NAGLU in TET2 CD cells was further confirmed by RT-qPCR analysis, and expression of these three genes was shown to be anticorrelated with TET2 expression levels in the breast cancer TCGA cohort of patients (n = 1,218), validating our in vitro observations." (PMID 35351824, 2022). "TET2 could inhibit the migration and invasion of breast cancer cells through the demethylation of EpCAM and E-cadherin, again preceding their expression and activation." (PMID 34885145, 2021). "In this study, we set out to investigate the relationship between TET2 and PD-L1 in breast cancer." (PMID 34064441, 2021). "Conversely, our work suggests a tumor-suppressive role of TET2 in ERα+ breast cancer." (PMID 34885145, 2021). "The findings of our study suggest that the tumor microenvironment may modulate the expression of PD-L1 gene in breast cancer through targeting the TET2/HDAC complex." (PMID 34064441, 2021). "Researchers found that the nucleus of the unmutated breast cancer cells was 5hmC-positive, while the 5hmC in TET2-mutated tissue was negative." (PMID 32375881, 2020).